TARBP2 (TARBP2 subunit of RISC loading complex)
Diseases named in the same sentence as TARBP2 in open-access papers (continued):
Sharing a sentence is not in itself a finding about the gene and the disease.
tumor (24 papers, 2013 to 2024). "Above data have revealed that TARBP2 SUMOylation is potentially linked to its function of inhibiting tumour progression; therefore, next we attempted to explore the underlying molecular mechanism." (PMID 26582366, 2015). "SUMOylation of TARBP2 are implicated in suppression of tumor growth and tumor cell migration." (PMID 36911524, 2023). "Additionally, TARBP2 expression in tumor tissues showed a trend of association with the BCLC stage (Chi-square test p-value = 0.029) and portal vein tumor thrombus (PVTT) (Chi-square test p-value = 0.036)." (PMID 34249676, 2021). "Additionally, rs417309 of DGCR8, rs3742330 and rs13078 of DICER1, and rs784567 of TARBP2 as well as rs11077 of XPO5 are associated with the progression of LC depending on the tumor size and lymph node metastases." (PMID 26688807, 2015). "Furthermore, the DGCR8 rs1640299, DICER1 rs3742330 and rs13078, RAN rs14035, and XPO5 rs11077 as well as rs784567 of TARBP2 genes single nucleotide polymorphisms have demonstrated an association with tumor progression depending on the lymph node metastases." (PMID 26688807, 2015). "Colony formation and transwell invasion assays together showed that TARBP2 overexpression inhibited GC cell proliferation and invasion, indicating TARBP2 plays a tumor suppressive role in GC progression." (PMID 38806480, 2024). "TARBP2 plays a role in microRNA biogenesis of miR-1306 and miR-33a, which exert tumor suppressive roles by co-targeting TCF4 in GC." (PMID 38806480, 2024). "In this study, we showed that TARBP2 overexpression inhibited GC progression by regulating the expression of two tumor suppressive microRNAs (miR-1306 and miR-33a)." (PMID 38806480, 2024). "From the expression level, four RBPs (RBM10, PUM2, QKI2, and TARBP2) were downregulated in tumor tissues compared with normal tissues, while other identified RBPs were consistently upregulated in OS cells." (PMID 37426488, 2023). "The level of TARBP2 (pg/mL) significantly decreased in tumor and tumor adjacent tissue, compared to the control tissue." (PMID 36613950, 2022). "TARBP2 and its protein were consistently found to be dysregulated in clinical specimens, including tumor/adjacent tissue samples and the peripheral blood derived from HCC patients and healthy controls." (PMID 34249676, 2021). "Collectively, these data demonstrated that TARBP2 and its protein was decreased in tumor tissues and blood from HCC patients or in HCC cell lines, consistent with previous observations." (PMID 34249676, 2021). "The molecular levels of TARBP2 were explored to demonstrate its impact on the clinical outcomes in HCC patients, showing association with tumor stages and the OS of HCC patients within three-year after initial diagnosis, after controlling gender and age." (PMID 34249676, 2021). "Higher HIF-1α (HIF-1αhigh) expression was observed in tumor tissues with higher TARBP2 (TARBP2high) levels, and vice versa." (PMID 35008634, 2021). "This loop reduced the expression of let-7f-5p and TARBP2 in tumor cells to a low level, which hindered the tumor suppressive effects of let-7f-5p and TARBP2." (PMID 32305960, 2020). "The in vivo evidence showed that TARBP2 was significantly decreased in SR tumor tissues, whereas Nanog expression was upregulated." (PMID 30657254, 2019). "Overexpression of TARBP2 induces tumor formation via inhibition of PKR phosphorylation and PKR‐mediated eIF2α phosphorylation." (PMID 30657254, 2019). "Accordingly, overexpression of TARBP2 decreased the level of sorafenib resistance in PLC5/SR cells, suggesting that TARBP2 functions as a tumor suppressor by sensitizing = HCC cells to sorafenib treatment." (PMID 30657254, 2019). "Data on TARBP2 mRNA expression in normal and tumor tissues were collected from 441 unique analyses in the Oncomine database." (PMID 30657254, 2019). "Compared with the control Vector, TARBP2-K52R substantially promoted while TARBP2-WT inhibited tumour cell migration." (PMID 26582366, 2015).
tumor (continued). "Bioluminescent imaging assessment was performed at 4 weeks after injection, showing that tumours in the TARBP2-K52R group were detected to be larger than those in the vector group, whereas tumours in the TARBP2-WT group were the smallest." (PMID 26582366, 2015). "The majority of ACC tumor cells were positive for TARBP2 nuclear expression (10/17), while five showed mixed nuclear staining and two cases were negative." (PMID 23671264, 2013). "Concordantly with the results obtained by RT-qPCR and western blot, most of the ACCs (14/17, 82%) showed strong cytoplasmic TARBP2 staining in nearly all tumor cells, while moderate TARBP2 expression was detected in only three ACCs (18%)." (PMID 23671264, 2013). "We further investigated the effect of TARBP2 deregulation on cell growth and apoptosis and explored possible mechanisms responsible for its deregulation in this tumor type." (PMID 23671264, 2013). "Notably, overexpressed or downregulated TARBP2 was found in various cancers, and the assumption of improvement in tumor angiogenesis and metastasis was verified through dysregulating miRNAs in lung, breast, and liver cancer cell lines." (PMID 37426488, 2023). "We identified the tumor suppressors repressed by TARBP2 through RNA sequencing." (PMID 36230863, 2022). "In addition, tumor biological functional experiments in sh-TARBP2 HepG2 cells after restoring the expression of SERPINE1 further linked the observed up-regulation of SERPINE1 in HCC with TARBP2 as the potential downstream regulator." (PMID 34249676, 2021). "In addition, the rs3742330 of DICER1, rs784567 of TARBP2, rs417309 of DGCR8, and rs14035 of RAN as well as rs11077 of XPO5 are associated with the LC progression depending on the tumor size." (PMID 26688807, 2015). "Interestingly, we observed that TARBP2 was localized both in the cytoplasm and nucleus of tumor cells, whereas its expression was mainly found in the cytoplasm of non-tumor cells." (PMID 23671264, 2013). "Moreover, we also investigated whether TARBP2 SUMOylation influences xenograft tumour growth in vivo." (PMID 26582366, 2015). "We observed significant over-expression of ADAR, ADARB1, DDX5/17/20, DGCR8, DICER1, DROSHA, EIF2C1-4 (AGO1-4), GEMIN4, POLR2A, TARBP2, TNRC6A and XPO5 in tumor tissue compared to adjacent mucosa." (PMID 31510013, 2019). "We transfected codon-optimized LT (LTco), tumor-derived truncated LT (LT339), and codon-optimized sT (sTco) into MCPyV− MCC cell lines and evaluated the effect on expression levels of DROSHA, DGCR8, DICER1, and TARBP2 using western blotting." (PMID 34761184, 2021). "Downregulation of TARBP2 increases Nanog and OCT4 expression and contributes to clonogenicity and tumor growth in Ewing sarcoma family tumors, suggesting that TARBP2 might exhibit potential as a central mediator in regulating the properties of CSC." (PMID 30657254, 2019). "TARBP2 SUMOylation does not influence the biogenesis of mature miRNAs, but it enhances the gene-silencing efficiency of miRNAs and suppresses tumor progression." (PMID 29020972, 2017).
TARBP2 also shares sentences with these, for which no sentence is quoted: osteosarcoma (3 papers); colon carcinoma (2); colorectal cancer (2); Alzheimer disease (1); astrocytoma (1); bladder cancer (1); cardiomyopathy (1); DICER1 syndrome (1); diffuse large B-cell lymphoma (1); Dystonia (1); dystonia 16 (1); HIV-1 infection (1); Huntington disease (1); infection (1); metastatic tumor (1); oligospermia (1); pancreatic cancer (1); papillary thyroid carcinoma (1); psoriasis (1); rhabdomyosarcoma (1); sarcoma (1); Sertoli-Leydig cell tumor (1); thyroid anaplastic carcinoma (1); thyroid cancer (1); urothelial bladder carcinoma (1); urothelial carcinoma (1); Wilms tumor (1).